IL4 (interleukin 4)
Diseases named in the same sentence as IL4 in open-access papers (continued):
Sharing a sentence is not in itself a finding about the gene and the disease.
malaria (continued). "During severe human malaria, the levels of IL-4 were higher in some studies and lower in others when compared to uncomplicated infections." (PMID 36839438, 2023). "Either increased or decreased levels of IL-4, IL-12, and IL-13 were observed in malaria monoinfection compared to dengue virus monoinfection." (PMID 36716305, 2023). "Among these 18 studies, ten studies reported higher IL-4 levels in severe malaria than in uncomplicated malaria (55.6%)." (PMID 35820892, 2022). "Meanwhile, higher mean IL-4 levels were observed in uncomplicated malaria than in healthy controls among studies that used plasma for IL-4 measurement (pooled MD 0.97 pg/mL, 95% CI −0.03 to 1.91 pg/mL, I2 97.15%, six studies)." (PMID 35820892, 2022). "In the current investigation, data on IL-4 levels in patients with severe and uncomplicated malaria were compiled." (PMID 35820892, 2022). "Nonetheless, a meta-analysis of case–control studies revealed a trend toward lower IL-4 levels in patients with severe malaria than in patients with uncomplicated malaria." (PMID 35820892, 2022). "Meanwhile, in two studies, higher IL-4 levels in severe malaria than in uncomplicated malaria were reported (33.3%)." (PMID 35820892, 2022). "Meanwhile, higher mean IL-4 levels were observed in uncomplicated malaria than in healthy controls among studies that enrolled only adults (pooled MD 1.05 pg/mL, 95% CI −0.54 to 1.56 pg/mL, I2 0%, two studies)." (PMID 35820892, 2022). "Higher IL-4 levels in uncomplicated malaria than in healthy controls were reported in 14 studies (58.3%)." (PMID 35820892, 2022). "The MD of IL-4 levels between severe (434 cases) and uncomplicated malaria (611 cases) was estimated using the data from 11 studies that reported quantitative data (mean and SD, or median and range) of IL-4 levels." (PMID 35820892, 2022). "The primary outcome measure was the difference in IL-4 levels between patients with severe malaria and patients with uncomplicated malaria." (PMID 35820892, 2022). "Meanwhile, lower IL-4 levels in severe malaria than in uncomplicated malaria were reported in five studies (27.8%)." (PMID 35820892, 2022). "As with the subgroup analysis of the method for IL-4 measurement, the meta-analysis of studies using ELISA revealed lower IL-4 levels in patients with severe malaria compared to patients with uncomplicated malaria." (PMID 35820892, 2022). "The meta-analysis revealed lower IL-4 levels in patients with severe malaria than in those with uncomplicated malaria, though a trend toward comparable IL-4 levels between both groups was more likely because several sources of heterogeneities were observed." (PMID 35820892, 2022). "The difference in IL-4 levels between uncomplicated malaria and healthy controls was reported in 24 studies." (PMID 35820892, 2022). "Among the 36 included studies, IL-4 levels in both severe and uncomplicated malaria were reported in 18 studies." (PMID 35820892, 2022). "IL-4 levels, conversely, were significantly lower in patients with severe malaria than in those with uncomplicated malaria in endemic areas compared to nonendemic areas, implying that it was a predictor of disease outcome in the endemic region." (PMID 35820892, 2022). "The meta-analysis results showed lower mean IL-4 levels in severe malaria (434 cases) than in uncomplicated malaria (611 cases) (P = 0.01, pooled MD: −3.36 pg/mL, 95% confidence intervals CI −5.55 to −1.16 pg/mL, I2: 98.15%, 11 studies)." (PMID 35820892, 2022). "The findings of this study will inform future research into IL-4 as a predictive biomarker for severe malaria." (PMID 35820892, 2022). "On the contrary, a meta-analysis of prospective observational studies demonstrated a trend toward higher IL-4 levels in patients with severe malaria than in patients with uncomplicated malaria." (PMID 35820892, 2022). "Next, increased IL-4 levels were in accordance with increased IL-4 receptors in patients with severe malaria." (PMID 35820892, 2022).
malaria (continued). "Next, the difference in IL-4 levels between uncomplicated malaria (635 cases) and healthy controls (674 cases) was estimated from 11 studies that reported quantitative data (mean and SD, or median and range) of IL-4 levels." (PMID 35820892, 2022). "For the meta-analysis of the difference in mean IL-4 levels between uncomplicated malaria and healthy controls, results showed the funnel plot's asymmetry that demonstrates the distribution of MDs and standard error of IL-4 among the included studies." (PMID 35820892, 2022). "Second, studies conducted in Europe homogeneously showed higher IL-4 levels in uncomplicated malaria than healthy controls." (PMID 35820892, 2022). "The tertiary outcome was the difference in IL-4 levels between patients with uncomplicated malaria and healthy control." (PMID 35820892, 2022). "Nonetheless, several sources of heterogeneity of outcomes, including study designs, types of severe complications, malaria parasitaemia, and method for IL-4 measurement, were observed." (PMID 35820892, 2022). "Meanwhile, lower IL-4 levels in uncomplicated malaria than in healthy controls were reported in four studies (16.7%)." (PMID 35820892, 2022). "Several previous studies have shown elevated levels of type 2 anti-inflammatory cytokines IL-10 and IL-4 in the malaria-infected group." (PMID 33422078, 2021). "The IL4 VNTR 1R allele was associated with severe malaria with increased plasma IL4 level and reduced risk of severe malaria, while the IL4 VNTR 2R allele was associated with decreased plasma IL4 level." (PMID 34698295, 2021). "The only exception was for TNF-α/IL-4 which was significantly increased in children with microscopic asymptomatic malaria compared to uninfected controls using the Mann-Whitney test (p = 0.044)." (PMID 33281757, 2020). "On the other hand, IL-4 was found to increase significantly in children with microscopic and submicroscopic malaria compared to controls." (PMID 33281757, 2020). "The levels of anti-inflammatory cytokines, IL-4 and IL-10 in children with microscopic asymptomatic malaria, submicroscopic asymptomatic malaria and uninfected controls were compared." (PMID 33281757, 2020). "IFN-γ-/- and IL-4-/- mice had lower numbers of malaria parasites in the liver after SPZ challenge compared with B6 WT mice even without S. mansoni infection." (PMID 29373600, 2018). "It is well known that regulation of pro-inflammatory (IFN-γ, TNF-α, IL-6, IL-17) and anti-inflammatory (IL-10, IL-4) cytokines play a pivotal role in malaria parasite growth, protection, and/or pathogenesis." (PMID 29892278, 2018). "In the pathogenic process of malaria, the cellular immune response is mediated by Th1 profile T cell lymphocytes with IFN-γ production and Th2 profile, with IL-4 and IL-5 cytokines, to eliminate the parasite." (PMID 30126413, 2018). "Many individuals with asymptomatic malaria display multiple significant interactions involving IL-4." (PMID 30126413, 2018). "Malaria-induced antibody production and pathology were unaltered by 11β-HSD1 deficiency though plasma levels of IL-4, IL-6 and TNF-α were slightly affected by 11β-HSD1 deficiency, dependent on the infecting parasite." (PMID 29062028, 2017). "The data analysis demonstrated that both malaria groups have significantly increased levels of IL-2, IL-4, IL-6, IL-10, TNF and IFN-γ as compared to the endemic controls." (PMID 27581163, 2016). "In the present study, plasma levels of IL-4, IL-7, IL-12p70, and IL-13 were more elevated in subjects purely with dengue fever than in those with malaria mono-infection or malaria and dengue co-infection." (PMID 26271921, 2015). "For example, Eotaxin alone has a marginal effect when EC are compared to malaria patients, whereas it becomes significant when calculated with covariates (IL-4 and IL-10)." (PMID 26602091, 2015).
malaria (continued). "This conclusion was presaged by previous work in this infection that indicated poor Th1 commitment, as measured by IL-4 production and help for malaria-specific antibody by T cells late in infection." (PMID 26646149, 2015). "It is known that the expression of anti-inflammatory cytokines such as IL4 and IL10 is critical in the control of anaemia and severe malaria and the expression of these cytokines is associated with biochemical patterns of iron deficiency in infected children." (PMID 25890318, 2015). "IL-4 and IL-13 plasma levels were also previously found to be higher in dengue fever compared to malaria cases." (PMID 26271921, 2015). "The proportion of individuals with IL-4–producing lymphocytes in responses to parasite Ag was higher among the Fulani, who are more resistant to malaria, than the sympatric group of Dogon." (PMID 24453249, 2014). "This is also consistent with linkage analyses in mice and genetic studies in humans showing an association of IL3, IL4, IL13, IRF1, and ARHGAP26 with parasitaemia, mild malaria or severe malaria." (PMID 24884991, 2014). "We show in this article that children who induced DBLα-tag specific IL-4+CD4+ T cell responses had a delayed time to subsequent malaria episodes over the next year." (PMID 24453249, 2014). "The study also shows that individuals with asymptomatic malaria displaying multiple significant interactions involving IL-4." (PMID 24741587, 2014). "Immunity to blood stage malaria parasites is thus primarily conferred by humoral immune responses in which the participation of IL-4 producing CD4 Th2 cells and B cells are of major importance." (PMID 24465641, 2014). "IL-4 has further been shown to be an erythropoietic inhibitor whose elevated production can aggravate severe malaria." (PMID 23521898, 2013). "IL-4, despite being at low systemic levels, seems to be a central mediator with several significant interactions in individuals with asymptomatic malaria." (PMID 23433077, 2013). "Intriguingly, in the group of individuals with asymptomatic malaria, the complexity of the network was restored and several significant interactions were detected, but with a clear central role for IL-4." (PMID 23433077, 2013). "Variations in several host genes (HBB, IL4, IL12, TNF, LTA, NCR3 and FCGR2A) have been reported to be associated with malaria outcome." (PMID 24066864, 2013). "In conclusion, IL-4 -590T, -34T and intron-3 VNTR R2 allele is associated with enhanced survival against malaria and other extracellular pathogens in Indian populations." (PMID 23110190, 2012). "Studies have revealed that INF-γ levels were significantly elevated during early stages of malaria, whereas the IL-4 levels were elevated during intermediate and late stages indicating a switch towards Th2 response." (PMID 23110190, 2012). "Uninfected olive baboon placentas expressed significantly higher levels of IL-4, IL-6 and IL-10 compared to malaria infected placentas, indicating that higher levels observed in this panel of cytokines were maintained in uninfected placentas." (PMID 26623293, 2012). "These include HBB, IL4, TNF, and FCGR2A, which have also been associated with both malaria resistance and IgG levels." (PMID 22947458, 2012). "The linkage or association of HBB, IL4, IL12, TNF, LTA, and NCR3 with mild malaria or parasitaemia has been previously reported in a population living in Burkina Faso." (PMID 22947458, 2012). "The participation of IL-4 in the humoral immune response to malaria involves the production of class IgG1 and IgG3 antibodies, which are involved in the response against the antigens of parasite erythrocytic stages." (PMID 21917128, 2011). "Those SNP associations with severe malaria are well known and are commonly reported in the literature: CR1, IL4, TNF, G6PD, IL10." (PMID 20459687, 2010). "Complicated malaria patients with previous malaria experiences carrying IL4-590TT genotype had significantly lower levels of anti-P." (PMID 20003246, 2009).
malaria (continued). "It is possible that IL4-590°C or T in combination with previous exposure to malaria antigens probably partly modify the antibody isotype profiles and thus represent a wide spectrum of clinical symptoms." (PMID 20003246, 2009). "falciparum IgG3 (P = 0.0156), while uncomplicated malaria patients with previous malaria experiences carrying the same genotype had significantly higher levels (P = 0.0206) compared to their IL4-590 counterparts." (PMID 20003246, 2009). "falciparum IgG subclass and IgE levels (median) separated by IL4-590 CT genotype in patients with complicated and uncomplicated malaria (CM, UCM)." (PMID 20003246, 2009). "falciparum IgG3 levels were observed only among patients with complicated malaria carrying IL4-590 TT genotype compared to their counterparts." (PMID 20003246, 2009). "Both IL-4 and IL-13 signaling through the IL-4R mediate type 2 (humoral, as opposed to type 1 cellular) immunity against helminths, toxins and tropical parasites such as plasmodium (malaria) and trypanosomes (African sleeping sickness/Chagas disease)." (PMID 38577257, 2023). "The IL-4 level was increased in asymptomatic malaria and HBV coinfections." (PMID 36716305, 2023). "However, a meta-analysis of the results from various studies has shown an average lower IL-4 serum concentration during severe disease in comparison to uncomplicated malaria." (PMID 36839438, 2023). "Searches for relevant articles on IL-4 levels in patients with severe malaria and studies that examined IL-4 levels in both uncomplicated malaria and healthy controls were performed in PubMed, Embase, and Scopus using the search strategy without limitation to publication years or language." (PMID 35820892, 2022). "IL-4 levels in both uncomplicated malaria and healthy controls were reported in 24 studies." (PMID 35820892, 2022). "This bias indicated the missing results of related studies; hence, the investigation of IL-4 levels between severe and uncomplicated malaria, as well as between uncomplicated and healthy controls, is crucial for confidence in the conclusion made by the meta-analysis." (PMID 35820892, 2022). "Further, the trim and fill method was applied to determine the effect size after adjusting for the small-study effect, and the results showed that the mean IL-4 levels were lower in severe malaria than in uncomplicated malaria (pooled MD −0.246 pg/mL, 95% CI −0.0.386 to −0.106) pg/mL)." (PMID 35820892, 2022). "The subgroup analysis of study designs revealed that uncomplicated malaria demonstrated higher mean IL-4 levels than healthy controls in case–control studies (pooled MD 2.79 pg/mL, 95% CI 0.70–4.87 pg/mL, I2 92.88%, four studies) and a cohort study (MD 70.2 pg/mL, 95% CI 37.08–103.32 pg/mL)." (PMID 35820892, 2022). "Alternatively, to this classic systematic review, individual patient data (IPD) meta-analysis could further provide insights for IL-4 levels in patients with malaria of varying severity." (PMID 35820892, 2022). "They hypothesized that elevated IL-4 levels in severe malaria could be explained by a switch from Th1 to Th2 responses during peak parasitaemia, with the latter playing a critical role in parasite clearance." (PMID 35820892, 2022). "Based on the trim and fill analysis, it might be beneficial if further studies could investigate IL-4, as the meta-analysis filled with missing studies showed lower IL-4 levels in patients with uncomplicated malaria than in healthy controls." (PMID 35820892, 2022). "Nevertheless, what role IL-4, a member of the Th2 group of cytokines, may play in the pathophysiology of severe malaria is unclear, and further research is required." (PMID 35820892, 2022). "Several studies investigated the IL-4 levels in different clinical malaria severity." (PMID 35820892, 2022).
malaria (continued). "Further, the trim and fill method was applied to determine the effect size after adjusting for the small-study effect, and results showed that mean IL-4 levels were lower in uncomplicated malaria than in healthy controls (pooled MD −0.398 pg/mL, 95% CI −0.469 to −0.3326 pg/mL)." (PMID 35820892, 2022). "IL-4 levels in both severe and uncomplicated malaria were reported in 18 studies." (PMID 35820892, 2022). "The meta-analysis demonstrated lower IL-4 levels in patients with severe malaria than in those with uncomplicated malaria, though a trend toward comparable IL-4 levels between the two groups was more likely because several sources of heterogeneity were observed." (PMID 35820892, 2022). "Importantly, three out of the four patterns for malaria had anti-inflammatory response cytokines in the clusters (IL-4, IL-13, IL-1RA)." (PMID 35811678, 2022). "From the trim and fill analysis, it might be beneficial if further studies could investigate IL-4 as the meta-analysis filling, with missing studies showing lower IL-4 levels in patients with severe malaria than in those with uncomplicated malaria." (PMID 35820892, 2022). "Thus, the trend toward lower IL-4 levels in patients with severe malaria compared to patients with uncomplicated malaria observed in case–control, cohort, and cross-sectional studies was more confident, as these studies were of high quality." (PMID 35820892, 2022). "Thus, a trend toward lower IL-4 levels in children with severe malaria than in those with uncomplicated malaria was clearly demonstrated." (PMID 35820892, 2022). "Additionally, to prevent severe malaria, IL-4 and IL-10 can directly downregulate IL-6, TNF-α, and IL-1β." (PMID 35820892, 2022). "Thus, in the current investigation, data on IL-4 levels in patients with severe and uncomplicated malaria were compiled." (PMID 35820892, 2022). "The subgroup analysis of types of methods for IL-4 measurement revealed that studies that used ELISA demonstrated lower mean IL-4 levels in patients with severe malaria than in uncomplicated malaria patients (pooled MD −15.14 pg/mL, 95% CI −20.71 to −9.57 pg/mL, I2 98.71%, seven studies)." (PMID 35820892, 2022). "Furthermore, elevated levels of IL-17 with high levels of IL-4, IL-12 and IFN-γ were associated with haemoglobin loss in malaria recovered semi-immune mice." (PMID 33422078, 2021). "As T-cell-mediated immunity plays a crucial role to clear blood-stage parasite malaria parasite and IL-4-controlled CMI activating factor (IFN-γ), we determined IL-4 and IFN-γ responses against EL-PfMSP-Fu24 and plain PfMSP-Fu24 when delivered through topical and intramuscular route." (PMID 33562617, 2021). "It has been highlighted that dendritic cells release IL-4 early during malaria and in this case, IL-4 may contribute to the development of a severe form of malaria." (PMID 34790829, 2021). "The role of IL-4, an important regulator of Th2 responses, is incompletely elucidated in malaria." (PMID 34790829, 2021). "We observed increased levels of cytokines such as TNF-α and IL-6 in children with microscopic asymptomatic malaria, whereas, IFN-γ, IL-17A, and IL-4 levels were increased in infected children with microscopic or submicroscopic asymptomatic malaria compared with uninfected controls." (PMID 33281757, 2020). "However, compared with the other groups, anti-inflammatory cytokines including IL-10 and IL-4, were lower in women with Malaria+CHB." (PMID 31002731, 2019). "Presence of detectable IL4 by severe malaria diagnosis and filarial serology status, n(%)." (PMID 29579050, 2018). "Overall, these data show that 11β-HSD1 deficiency increases IL-4 levels in response to PcAS infection, but does not influence malaria-associated antibody production or pathology." (PMID 29062028, 2017).